AQP1 (aquaporin 1 (Colton blood group))
Diseases named in the same sentence as AQP1 in open-access papers (continued):
Sharing a sentence is not in itself a finding about the gene and the disease.
pancreatitis (5 papers, 2014 to 2026). Inflammation of the pancreas. "In the context of gene therapy for pancreatic disorders such as pancreatitis, adenoviral vectors encoding AQP1 or AQP5 may represent additional tools." (PMID 31614661, 2019). "Previous studies have demonstrated that the expression of AQP1 is related to lung injury induced by pancreatitis and oleic acid." (PMID 35450040, 2022). "Despite several studies, the role of AQP1 in pancreatitis has not been fully understood." (PMID 31614661, 2019). "It would be worth assessing whether CFTR corrector and potentiator are also able to correct AQP1 expression in animal models of pancreatitis." (PMID 31614661, 2019). "The involvement of AQP1 in the pathophysiology of pancreatitis has been already raised previously." (PMID 30050452, 2018). "The loss of AQP1 itself does not damage the pancreas and does not cause pancreatitis in mice, which assuming the compensating effect of AQP5; however, induces a more severe disease progression." (PMID 30050452, 2018). "In order to test the hypothesis that AQP1 may be involved in the pathomechanism of pancreatitis, we investigated the severity of cerulein-induced AP in WT and AQP1 KO mice." (PMID 30050452, 2018). "In the next step, we studied the effect of pancreatitis-inducing factors on the expression of AQP1." (PMID 30050452, 2018). "Moreover, we have found that AQP1 plays role in the pathology of pancreatitis." (PMID 30050452, 2018). "Using in vitro models, human tissues and transgenic mice, we have shown that AQP1 plays essential role in ductal fluid and HCO3- secretion, lack of CFTR decreases its expression and deletion of AQP1 is strongly associated with increased susceptibility of the gland to pancreatitis." (PMID 30050452, 2018). "Overall, these results indicate that in the absence of AQP1 the course of pancreatitis is more severe." (PMID 30050452, 2018). "HCO3- and fluid secretion significantly decreased in AQP1 KO versus WT mice and the absence of AQP1 also worsened the severity of pancreatitis." (PMID 30050452, 2018). "So in the next step, we investigated whether the lack of AQP1 has any effects on the progression of pancreatitis." (PMID 30050452, 2018). "Since we found that the lack of AQP1 exacerbates the course of cerulein-induced pancreatitis in mice, we tested whether this water channel is also involved in the pathomechanism of pancreatitis in humans." (PMID 30050452, 2018). "In contrast to AQP1, AQP3 is not expressed in the mouse pancreas and this isoform is either involved in tumor progression than pancreatitis." (PMID 30050452, 2018). "We have chosen to focus on AQP1, since this isoform is abundantly expressed in both acinar and ductal cells of mouse and human pancreas and the role of this AQP has not been evaluated in pancreatitis yet." (PMID 30050452, 2018).
peritonitis (5 papers, 2015 to 2025). Inflammation of the peritoneum (tissue that lines the abdominal wall and covers most of the organs in the abdomen). "However, it is not clear that the therapeutic effect of the PPAR-γ agonist on a PD rat model with LPS-induced peritonitis is associated with regulation of AQP1 and ZO-1 expression." (PMID 29871973, 2018). "Conversely, 90 min-PD treatment in the LPS-induced peritonitis rats is enough to decrease AQP1 and ZO-1 expression." (PMID 29871973, 2018). "As expected, acute peritonitis in Aqp1+/+ mice was reflected by a massive, submesothelial infiltrate of mononuclear cells including macrophages (F4/80 staining)." (PMID 25719758, 2015). "The decreased infiltration of Aqp1-/- macrophages in the peritonitis model was in full agreement with the abrogation of LPS response in vitro." (PMID 25719758, 2015). "Additionally, it has been reported that the expression of AQP1, present in macrophages, regulated their migration in a murine model of peritonitis, showing that functional AQP1 suppresses the migration of resting macrophages." (PMID 33321760, 2020). "Similarly, our present study also demonstrated that rosiglitazone dose-dependently increased the expression of AQP-1 in the peritoneum of LPS-induced peritonitis rats." (PMID 29871973, 2018). "Additionally, AQP1’s roles in cell migration, wound healing, tumor growth and dissemination may contribute to EMT; vascular proliferation, and leukocyte recruitment during inflammation, in conjunction with peritonitis, can lead to UFF." (PMID 39724420, 2025).
portal hypertension (5 papers, 2014 to 2025). Increased blood pressure in the portal venous system. "This indicates that portal hypertension induced AQP1 expression in peritoneal endothelium through Piezo1 in a murine model of liver cirrhosis." (PMID 41034523, 2025). "Third, in TAA/CCl4 + PPVL-treated mice, AQP1 expression in LSECs decreased significantly in Piezo1△EC mice compared with Piezo1flox/flox mice, indicating that portal hypertension induced AQP1 expression in LSECs through Piezo1." (PMID 41034523, 2025). "Our study revealed that portal hypertension induced AQP1 expression in peritoneal endothelial cells." (PMID 41034523, 2025). "Nevertheless, after bile duct ligation AQP1-KO mice have reduced angiogenesis, reduced fibrosis, and less portal hypertension, suggesting a prominent role for AQP1 in the pathological changes often observed during chronic liver diseases." (PMID 31023968, 2019). "The role of AQP1 in angiogenesis, fibrosis and portal hypertension in cirrhotic mice has been investigated in AQP1 knockout mice, which showed reduced angiogenesis and fibrosis." (PMID 29977890, 2018). "Aquaporin-1 (AQP1), confirmed to be regulated by osmotically sensitive miRNAs, promotes angiogenesis, fibrosis, and portal hypertension after bile duct ligation." (PMID 24812632, 2014). "This reveals that portal hypertension induced AQP1 expression in the peritoneum." (PMID 41034523, 2025).
primary Sjögren's syndrome (5 papers, 2016 to 2024). "Gene therapy using recombinant adenoviral or adeno-associated viral vectors coding for AQP1 (AdhAQP1) were capable to restore saliva flow to irradiated salivary glands of animals and human with Sjögren’s syndrome, as well as to resolve inflammation." (PMID 37681902, 2023). "In the clinic, patients with radiotherapy for head and neck cancer or with Sjögren’s syndrome represent ideal target populations for AQP1 gene therapy." (PMID 37681902, 2023). "Treatment of a patient suffering from Sjögren’s syndrome with Rituximab reverted the decreased AQP1 expression detected in the salivary gland." (PMID 37681902, 2023). "Further studies are necessary to better understand the role of both AQP5 and AQP1 in xerostomia resulting from Sjögren’s syndrome." (PMID 26828482, 2016). "Rituximab increased AQP1 expression in myoepithelial cells and saliva flow in patients suffering from Sjögren’s syndrome." (PMID 26828482, 2016). "Interestingly, AQP1 expression in labial salivary glands is selectively downregulated in patients with primary Sjögren's syndrome 11, and this decrease in AQP1 in the salivary gland may play a crucial role in the pathology of this disease." (PMID 29321959, 2018). "The study aims to assess the diagnostic and clinical significance of autoantibodies against aquaporin-1 (anti-AQP1) and aquaporin-5 (anti-AQP5) in primary Sjögren’s syndrome (pSS)." (PMID 39441465, 2024). "A decrease in AQP1 expression has been documented in labial salivary glands biopsies from patients suffering from Sjögren’s syndrome, while no change has been detected in endothelial cells." (PMID 26828482, 2016).
prostate adenocarcinoma (5 papers, 2018 to 2023). "For the first time, Park and Yoon (2017) reported that AQP1 can perform as a prognostic factor for biochemical recurrence in prostate adenocarcinoma." (PMID 36672280, 2023). "A study assessed the AQP1 expression and their clinico-pathological significance in prostate adenocarcinoma." (PMID 36672280, 2023). "Furthermore, in prostatic adenocarcinoma cell lines, AQP1 was suppressed by ginsenoside Rg3, together with cell migration." (PMID 33807998, 2021).
brain cancer (4 papers, 2016 to 2022). A primary or metastatic malignant neoplasm affecting the brain. "In brain cancer, AQP1 expression is associated with brain capillary endothelial cells, which do not express AQP1 in normal brain tissue." (PMID 31803626, 2019). "As in the case of AQP1 upregulation in brain cancer, one of these molecules is VEGF, which can promote tumor neovascularization, vessel permeability, and extravasation of plasma proteins into extracellular brain spaces." (PMID 27367682, 2016). "Interestingly, AQP1 expression in brain cancer is associated with BCECs, which do not express this AQP in normal brain; this observation suggested that AQP1 up-regulation can be involved in vasogenic edema." (PMID 27367682, 2016).
Cerebral ischemia (4 papers, 2011 to 2022). Restriction of arterial blood supply to the brain associated with insufficient oxygenation to support the metabolic requirements of the tissue. "In rat cerebral ischemia miR-320a inhibits AQP1 and AQP4 expression, whereas anti-miR-320a upregulates AQP1 and AQP4 expression, identifying miR-320a as a potential modulator of these AQPs." (PMID 35036988, 2022). "Further, it seems likely that AQP1 is involved in pulmonary or brain edemas produced by hypoxic events, such as those observed in acute mountain sickness or in cerebral ischemia due to vascular injury." (PMID 22174795, 2011). "miR-320a was reported to inhibit AQP1 and AQP4 gene expression both in vitro and in vivo in a cerebral ischemia rat model, whereas anti-miR-320a upregulated AQP1 and AQP4 expression with consequent reduction of infarct volume." (PMID 29977890, 2018).
cholestasis (4 papers, 2022 to 2025). Impairment of the bile flow caused by obstruction within the liver, or outside the liver in the bile duct system. "Hepatocyte-induced AQP1 using adenoviruses improves estrogen-induced and lipopolysaccharide-induced cholestasis in rats." (PMID 39335570, 2024). "Additionally, AQP8 and AQP9 expression is reduced in the livers of rats with ligated bile ducts, whereas increased AQP1 expression alleviates cholestasis." (PMID 40115259, 2025).
clear cell renal cell carcinoma (4 papers, 2014 to 2025). "Furthermore, AQP1 has been identified as an autonomous prognostic factor and a prognostic-related factor in clear cell renal cell carcinoma (ccRCC)." (PMID 37904849, 2023). "The presence of urinary AQP1 was not limited to patients with papillary and clear cell renal carcinomas in this study; patients with postoperative pathology reports of oncocytoma, benign cystic nephroma, and chromophobe renal cell carcinoma all had notable AQP1 bands via immunoblotting." (PMID 24803718, 2014). "Similar to AQP1, AQP9 is upregulated in clear cell renal cell carcinoma (ccRCC) tissues compared to normal tissues, and upregulation of AQP9 can correlate with aggressive progression and poor survival in ccRCC patients." (PMID 36389709, 2022).
endometriosis (4 papers, 2020 to 2023). The growth of functional endometrial tissue in anatomic sites outside the uterine body. "Suppression of AQP1 alleviates adhesion and angiogenesis of ectopic endometrial cells for murine endometriosis models via activation of the Wnt pathway." (PMID 36059959, 2022). "ZWINT and AQP1 may be reliable predictors of the severity of endometriosis, with high specificity and sensitivity." (PMID 35585523, 2022). "AQP1 might have a role in endometriosis via the Wnt/β-catenin signaling pathway." (PMID 33321760, 2020). "Through Lasso algorithm, four characteristic genes were determined among the shared endometriosis-related genes, containing BGN, AQP1, ELMO1, and DDR2." (PMID 36059959, 2022). "In the two datasets, higher levels of BGN, AQP1, ELMO1, and DDR2 were confirmed in endometriosis than normal endometrium tissues." (PMID 36059959, 2022). "Altogether, our research determined four characteristic genes (BGN, AQP1, ELMO1, and DDR2) with the favorable efficacy in diagnosing endometriosis." (PMID 36059959, 2022). "Through the Lasso approach, we determined four characteristic genes among endometriosis-related genes, containing BGN, AQP1, ELMO1 and DDR2." (PMID 36059959, 2022). "The AUCs (95%CI) of AQP1, BGN, DDR2, and ELMO1 were 0.96 (1.00–0.89), 0.98 (1.00–0.95), 1.00 (1.00–0.99), and 0.99 (1.00–0.98), respectively, demonstrating that each characteristic gene enabled to diagnose endometriosis accurately and sensitively." (PMID 36059959, 2022).
invasive breast carcinoma (4 papers, 2016 to 2024). A carcinoma that infiltrates the breast parenchyma. "AQP1 was positively correlation with leptin in invasive breast carcinoma, showing that leptin is associated with AQP1." (PMID 38791252, 2024). "AQP1 showed a high positive Spearman correlation coefficient (0.503) among the genes co-expressed with leptin in invasive breast carcinoma." (PMID 38791252, 2024). "In our clinical study, we reported for the first time that AQP1 was localized dominantly in the cytoplasm of cancer cells of invasive breast cancer patients and cytoplasmic AQP1 was an independent prognostic factor." (PMID 26812884, 2016). "In our present study, we used a large cohort of human invasive breast cancer specimens to investigate the expression and function of AQP1." (PMID 26812884, 2016).
invasive ductal carcinoma (4 papers, 2016 to 2023). "Benign breast lesions and ductal carcinoma in situ samples express AQP1 on the membrane of myoepithelial cells of the ducts, but the majority of invasive ductal carcinoma samples predominantly express AQP1 in the cytoplasm." (PMID 30678106, 2019). "Completely different from the membranous expression of AQP1 in myoepithelial cells of ducts in breast benign lesions and ductal carcinoma in situ (DCIS), we reported for the first time that AQP1 exhibited cytoplasmic expression pattern in cancer cells of invasive ductal carcinoma (IDC)." (PMID 26812884, 2016).
kidney injury (4 papers, 2019 to 2024). Trauma to the kidney. "In an in vitro model of septic acute kidney injury, overexpression of AQP1 promoted cell viability and reduced apoptosis, while in Chinese hamster ovary K1 cells, AQP1 overexpression induced apoptosis." (PMID 36142499, 2022). "In addition, it has been reported that AQP1 levels in the proximal tubule together with AQP2 levels in the collecting duct are decreased in I/R-induced kidney injury, which results in impaired urinary osmolality." (PMID 35280255, 2021). "Therefore, the increase in the number of proliferative cells may result in reduction of the renal expression of AQP1 and AQP2 at a later phase of cisplatin-induced kidney injury." (PMID 30744167, 2019).
ovarian tumor (4 papers, 2017 to 2021). "Our findings suggest that β-catenin and AQP1 are expressed in a sub-group of ovarian tumors and play important roles in carcinogenesis." (PMID 33807998, 2021). "AQP1 has been shown to be present in the microvascular endothelium of ovarian tissue but rarely in ovarian tumor cells." (PMID 33271827, 2020). "There is also a positive correlation between AQP1 expression and the occurrence of ascites and the progression of an ovarian tumor." (PMID 33271827, 2020). "AQP1 protein expression was upregulated in the late stages of ovarian tumors, but the positive or negative associations with survival rates of patients depended on the cancer subtype category." (PMID 32679804, 2020). "Interestingly, AQP1 localization in the ovary is comparable to its localization in the vagina, i.e., in the microvascular and in the epithelial cells of small blood vessels, and its expression is rarely present in ovarian tumor cells." (PMID 33271827, 2020).
Pleural effusion (4 papers, 2012 to 2022). The presence of an excessive amount of fluid in the pleural cavity. "The presence of pleural effusions in MPM has led to the hypothesis of an involvement of AQP1 in the disease." (PMID 35741021, 2022). "In addition, AQP1 plays a role in the equilibration of the osmotic gradient in pleural effusions, as well as the proliferation, movement, and anchorage-independent growth in MPM." (PMID 35741021, 2022). "Increased VEGF levels in pleural effusions of MM patients are associated with adverse prognosis, and VEGF has been implicated in the development in malignant pleural effusion by increasing vascular permeability, not dissimilar to the function of AQP1." (PMID 29104239, 2017).
Polyhydramnios (4 papers, 2016 to 2023). The presence of excess amniotic fluid in the uterus during pregnancy. "Hence, upregulation of AQP8 in the foetal membranes after AQP1 depletion may lead to polyhydramnios through a compensatory mechanism, while the expression of AQP9 in the placenta and foetal membranes is decreased after AQP1 depletion." (PMID 32542408, 2020). "Intriguingly, this group subsequently discovered that in pregnancies with polyhydramnios, AQP1 expression was enhanced in all regions of the foetal membrane, demonstrating that alterations in AQP1 expression might be a compensatory response but not the primary aetiolgy of idiopathic polyhydramnios." (PMID 32542408, 2020).
pulmonary diseases (4 papers, 2011 to 2022). "Nonetheless, related research from our laboratory has indicated changes in the expression pattern of AQP1 in lungs of patients with pulmonary diseases that can cause severe hypoxemia, such as cancer and interstitial lung disease." (PMID 22174795, 2011). "Aquaporin-1 (AQP-1) is expressed in lung endothelial cells and regulates water transport; thus, AQP-1 plays an important role in a number of edema-associated lung diseases." (PMID 25371738, 2014). "Furthermore, studies on different lung disorders support the assumption that AQP1 water channels play a role in various lung diseases." (PMID 33918079, 2021).
squamous cell carcinoma (4 papers, 2014 to 2025). A carcinoma arising from squamous epithelial cells. "On the other hand, AQP1 is highly expressed in aggressive basaloid-like oro-hypopharynx squamous cell carcinomas with poor prognosis." (PMID 40386053, 2025). "Recently, AQP1 has been reported as a distinctive prognostic factor in various cancers, including breast, cervical, colorectal, hepatocellular, lung, renal, and squamous cell carcinomas 61,62." (PMID 40386053, 2025).
viral infection (4 papers, 2005 to 2023). "By using the HIE system, we found that HuNoV induced the expression of AQP1 at both the mRNA and protein levels in the context of virus infection." (PMID 35458572, 2022). "Having demonstrated that AQP1 expression was upregulated following transfection with complete HuNoV cDNA in Caco2 cells, further experiments were carried out in the context of virus infection." (PMID 35458572, 2022). "In this study, we found that HuNoV transfection induced the expression of AQP1, which was further confirmed in the context of virus infection." (PMID 35458572, 2022). "Furthermore, previous studies have indicated that viral infections and hypoxia result in pulmonary edema that is accompanied by the downregulation of AQP1 expression." (PMID 25009607, 2014). "In the current study, we found that HuNoV transfection induced the expression of aquaporin 1 (AQP1), which was further confirmed in the context of virus infection, whereas the enterovirus EV71 (enterovirus 71) did not have such an effect." (PMID 35458572, 2022). "In the context of virus infection, HuNoV but not the enterovirus EV71 induced AQP1 expression." (PMID 35458572, 2022).
acute respiratory distress syndrome (3 papers, 2013 to 2024). Progressive and life-threatening pulmonary distress in the absence of an underlying pulmonary condition, usually following major trauma or surgery. "Upregulation of AQP1 could be observed in acute lung injury and pulmonary fibrosis, whereas a downregulation was reported for acute respiratory distress syndrome, asthma, and adenoviral infections." (PMID 33918079, 2021).